TYK2 (tyrosine kinase 2)
Diseases named in the same sentence as TYK2 in open-access papers (continued):
Sharing a sentence is not in itself a finding about the gene and the disease.
colitis (8 papers, 2016 to 2024). Inflammation of the colon. "In addition, we noted a significant decrease in Butyrivibrio species (p = 0.03), when comparing between wild-type and Tyk2-deficient mice over the course of DSS-induced colitis." (PMID 27687690, 2016). "Variable expression of the TYK2 gene can lead to exacerbation of colitis by altering the local microflora of the gastrointestinal tract and hindering the rebuilding of the colonic mucosa of the gastrointestinal tract, as has been observed in TYK2 deficiency in functional models." (PMID 39518103, 2024). "Using three different mouse models with Tyk2 deletion and the AOM-DSS protocol for colitis-associated CRC, we demonstrate additive tumor-suppressive functions of Tyk2 in cancer cells and in the immune microenvironment." (PMID 36185806, 2022). "To investigate the role of Tyk2 in the development of CRC, we applied the AOM – DSS protocol for colitis-associated CRC to Tyk2ΔIEC, Tyk2ΔHem and Tyk2Δ/Δ mice." (PMID 36185806, 2022). "A recent study directly addressed the function of Tyk2 in experimental colitis using Tyk2 knockout mice." (PMID 26938566, 2016). "While the IL-23-IRE1α/XBP1 pathway in ILC3s may be protective in colitis, other IL-23 targets including JAK2 and TYK2 are pathogenic." (PMID 38722686, 2024). "The same publication showed that this TYK2 inhibitor could prevent colitis in two distinct murine models and a partner publication demonstrated the ability of deucravacitinib to prevent IL-23-induced skin inflammation in mice." (PMID 34290741, 2021). "However, it is in contrast to another report that demonstrated reduced experimental colitis in Tyk2−/− mice and suggested reduced Th1 and Th17 activity to be responsible for this observation." (PMID 26938566, 2016). "Qualitative analyses performed by the TEM-immunogold method revealed the distribution of the kinase TYK2 in the mitochondrial region, both in normal intestinal epithelial cells and in neoplastic cells, with a predominance of mitochondrial localization in patients diagnosed with colitis." (PMID 39518103, 2024). "These initial studies preceded the discovery of IL-23, with subsequent studies using Tyk2 KO mice revealing a crucial role for this JAK in IL-23 signaling, including an essential role in models for both dermatitis and colitis." (PMID 34290741, 2021).
colorectal cancer (8 papers, 2012 to 2026). A primary or metastatic malignant neoplasm that affects the colon or rectum. "Background/Objectives: The aim of this study was to examine the expression of TYK2 in colorectal cancer (CRC) and to determine the potential diagnostic and prognostic significance of this kinase." (PMID 39518103, 2024). "Based on the fact that colorectal cancer often develops in chronically inflamed colons, an additional assessment of TYK2 distribution was conducted in fresh tissue material obtained endoscopically on previously undiagnosed patients." (PMID 39518103, 2024). "Then, TYK2 expression analysis was performed to identify selected histopathological features of clinical importance for colorectal cancer." (PMID 39518103, 2024). "A genomic NGS screen showed colorectal cancer metastasis to the liver contained a TYK2 SNP (rs2304256, V362F), although the mechanism of this mutation was not investigated." (PMID 34439323, 2021). "We used Tyk2 knockout mice (Tyk2Δ/Δ) and mice with conditional deletion of Tyk2 in hematopoietic (Tyk2ΔHem) or intestinal epithelial cells (Tyk2ΔIEC) to assess their cell type-specific functions in chemically induced colorectal cancer." (PMID 36185806, 2022). "Similarly, in colorectal cancer cells, high resolution mass spectrophotometry identified TYK2 as a phosphorylation target of hepatocyte growth factor (HGF), which stimulates proliferation in these cells." (PMID 34439323, 2021). "Here, using a murine colorectal cancer (CRC) organoid-based transplantation mode, we identified TYK2 as a key factor controlling CRLM." (PMID 40991399, 2026). "The negative correlation of the TYK2 expression level with tumor size and Bd may suggest a beneficial role of this tyrosine kinase in the pathogenesis of colorectal cancer." (PMID 39518103, 2024).
hyper-IgE syndrome (7 papers, 2012 to 2020). A condition that is characterized by elevated serum IgE, dermatitis, and respiratory infections. "The importance of the IL-17R pathway has been observed not only in knockout mouse models, but also in humans with rare genetic mutations that impact generation of Th17 cells or the IL-17 signaling pathway, including Hyper-IgE Syndrome (STAT3 or TYK2 mutations) or IL17RA or ACT1 gene deficiency." (PMID 25849644, 2015). "The first patient described with Tyk2 mutation suffered from hyper-IgE syndrome (HIES) and presented with viral, bacterial, and mycobacterial infections." (PMID 28184222, 2017). "Although homozygous recessive tyrosine kinase 2 (TYK) deficiency also can present with primary immunodeficiency with mild IgE elevation, STAT3 mutations are the predominant cause of sporadic and familial hyper-IgE syndrome." (PMID 33271763, 2020).
Arthritis (6 papers, 2005 to 2025). Inflammation of a joint. "A study using TYK2−/− mice also observed that TYK2−/− mice were less susceptible to collagen-induced arthritis (CIA) and had a lower incidence of arthritis compared with wild type (WT) mice." (PMID 30974919, 2019). "It should be noted that the B10.Q strain used in this study is different from the B10.Q mouse available from Jackson Laboratories, which has an arthritis-protective mutation of the Tyk2 gene, which explains the earlier reported resistance in these animals to G6PI-induced arthritis." (PMID 16277685, 2005).
colon cancer (6 papers, 2014 to 2024). "Case-control studies, using more than 1550 patients with colon cancer and 750 cases of rectal cancer, demonstrated that JAK2, SOCS2, STAT1, STAT3, STAT5A, STAT5B, and STAT6 were associated with colon cancer, and that STAT3, STAT4, STAT6, and TYK2 were linked to rectal cancer." (PMID 36982677, 2023). "Fifteen genes (DUSP2, INFGR1, IL6, IRF2, JAK2, MAP3K10, MMP1, NFkB1A, NOS2A, PIK3CA, SEPX1, SMAD3, TLR2, TYK2, and VDR) were significantly associated with colon cancer mortality at the <0.05 level; an additional 15 genes had gene PARTP values between 0.05 and 0.10." (PMID 25541970, 2014). "Fifteen genes (DUSP2, INFGR1, IL6, IRF2, JAK2, MAP3K10, MMP1, NFkB1A, NOS2A, PIK3CA, SEPX1, SMAD3, TLR2, TYK2, and VDR) were associated with colon cancer mortality (PARTP <0.05); JAK2 (PARTP = 0.0086), PIK3CA (PARTP = 0.0098), and SMAD3 (PARTP = 0.0059) had the strongest associations." (PMID 25541970, 2014). "In colon cancer, CLDN6 activates the TYK2/STAT3 pathway, which might suppress the migration and invasion abilities of colon cancer cells." (PMID 38731853, 2024).
Obesity (6 papers, 2015 to 2024). Accumulation of substantial excess body fat. "In human obese patients and obese mice, decreased TYK2 levels are associated with increased obesity." (PMID 28184222, 2017). "TYK2 has also been linked to the energy expenditure of cells, to the regulation of lipid metabolism, differentiation of brown adipose tissue, and obesity." (PMID 28184222, 2017). "Since obesity is an important risk for endocrinological disorders, we also analyzed the association between BMI and TYK2 promoter variant in T2D." (PMID 26288847, 2015). "POPs may also be linked to the development of obesity by increasing activation of the Notch pathway, by causing alteration of the TYK-2/STAT-3 pathway, and by increasing FABP expression and FAS upregulation, observed under in vitro conditions." (PMID 38255955, 2024). "Tyk2 knockout mice developed obesity and displayed insulin resistance." (PMID 39351529, 2024). "It is known that the alteration of the TYK-2/STAT-3 pathway can increase obesity development." (PMID 38255955, 2024). "Furthermore, altered BAT morphology and function were restored, and obesity was reversed in Tyk2 KO mice expressing CAStat3 in BAT." (PMID 39351529, 2024). "At least, as indicated in our study, TYK2 promoter variant in T2D was associated with non-obese patients but not with obesity." (PMID 26288847, 2015).
spondyloarthritis (6 papers, 2020 to 2025). "In the SKG murine model of spondyloarthritis, TYK2 inhibition was shown to reduce spondyloarthritis severity." (PMID 40709250, 2025).
systemic sclerosis (6 papers, 2021 to 2025). A chronic disorder, possibly autoimmune, marked by excessive production of collagen which results in hardening and thickening of body tissues. "TYK2 rs2304256 was verified to be closely related to systemic sclerosis susceptibility (SSc) in the European population, while the results were negative in the Chinese Han SSc population." (PMID 39726748, 2024). "Furthermore, multiple diseases characterized by overexpression of type I IFN—such as SLE, Sjögren syndrome, or systemic sclerosis—might benefit from selective Tyk2 inhibition." (PMID 36834806, 2023).
atopic dermatitis (5 papers, 2016 to 2025). "Ilunocitinib has a high potency for inhibition of JAK1, JAK2, and tyrosine kinase 2 (TYK2) and has been developed as a treatment for allergic and atopic dermatitis (AD) in dogs one year of age or older." (PMID 40660202, 2025).
dermatitis (5 papers, 2020 to 2025). An inflammatory process affecting the skin. "Tyrosine kinase 2 (TYK2) deficiency can be found in case of HIES characterized by severe dermatitis and a peculiar susceptibility to intracellular bacteria, for example, (mycobacteria, Salmonella) and viruses." (PMID 39945219, 2025). "Using the humanized Tyk2-V980I mouse, a TYK2-selective inhibitor, PF-06826647, was shown to be effective against murine dermatitis." (PMID 34290741, 2021). "This molecule has been shown to block IL-23 in vitro, and can suppress imiquimod-induced dermatitis in Tyk2-V980I mice." (PMID 34290741, 2021).
hepatocellular carcinoma (5 papers, 2018 to 2024). A malignant tumor that arises from hepatocytes. "Moreover, JAK2 and TYK2 were suggested to be potential biomarkers for the diagnosis of hepatocellular carcinoma." (PMID 33083484, 2020). "Increasing evidence demonstrates JAKs as a prognostic biomarker and therapeutic target for many cancers or other diseases, such as JAK3 for renal cell carcinoma, JAK2 for acute lymphoblastic leukemia, JAK2 for skin cutaneous melanoma, and TYK2 for hepatocellular carcinoma." (PMID 33083484, 2020). "Additionally, elevated tight junction proteins claudin-9 and claudin-17 stimulate migration and invasion of hepatocellular carcinoma (HCC) (liver cancer) cells through activation of the TYK2/STAT3 pathway." (PMID 34439323, 2021). "This is supported by a recently published meta-analysis of JAKs and STATs in hepatocellular carcinoma (HCC) patients, where normal or higher TYK2 levels correlated with longer survival and were found in healthy tissue." (PMID 31694222, 2019).
T-cell acute lymphoblastic leukemia (5 papers, 2014 to 2022). Acute lymphoblastic leukemia of T-cell origin. "Recent studies have highlighted TYK2 can act as an oncogene, with TYK2 activation increasing STAT1 phosphorylation and the expression of BCL-2 in T-cell acute lymphoblastic Leukemia and osteosarcoma." (PMID 35152270, 2022). "Preclinical studies on cell lines and mouse models have reported that the application of TYK2 inhibitors, including NDI-031301 and SAR-20351, induces tumor regression in T-cell acute lymphoblastic leukemia and solid cancers with significant survival benefits." (PMID 36531252, 2022).
T-cell lymphoma (5 papers, 2019 to 2025). "Examples include TRA::MTCP1 for T-PLL, TYK2 rearrangement for T-cell lymphomas; CCND1 and CCND2 rearrangement with IGK and IGL in mantle cell lymphoma; MYC rearrangements and hyperdiploidy in multiple myeloma." (PMID 40361363, 2025). "This includes anaplastic large-cell lymphoma with NPM1-ALK (anaplastic lymphoma kinase) and T-cell lymphoma with NPM1-TYK2 (tyrosine kinase 2)." (PMID 36834572, 2023). "CD4-NPM-ALK mice with intact Tyk2 developed aggressive T-cell lymphomas from about 12 weeks post-partum." (PMID 30131584, 2019). "In a T-cell lymphoma cell-line, whole-transcriptome screening found a TYK2 fusion protein with nucleophosmin (NPMI), NPMI-TYK2, which includes the kinase domain and a partial pseudokinase domain of TYK2." (PMID 34439323, 2021).
Alzheimer disease (4 papers, 2022 to 2026). A progressive, neurodegenerative disease characterized by loss of function and death of nerve cells in several areas of the brain leading to loss of cognitive function such as memory and language. "We find parallel neuroinflammatory mechanisms, dependent on TYK2 - a potential disease-modifying target - for TDP-43-associated Alzheimer's disease and C9ORF72-ALS." (PMID 41832177, 2026). "Partial inhibition of TYK2 mitigates tau pathologies in cells and mice, highlighting TYK2 as a potential therapeutic target for Alzheimer’s disease and other tauopathies." (PMID 39528671, 2024). "The signaling of one of the JAKs, TYK2-mediated STAT3, has been implicated in chronic inflammatory diseases, such as cancer and Alzheimer’s disease." (PMID 35563697, 2022). "Studies have shown that in mice, high amounts of Aβ intensify tyrosine phosphorylation and the transcriptional functioning of Tyrosine Kinase 2 (TYK2), which is related to high phosphorylation of STAT3 in brains with Alzheimer’s disease." (PMID 39861194, 2025).
fungal infections (4 papers, 2021 to 2024). "Human TYK2 mutations similarly result in increased susceptibility to bacterial, viral, and fungal infections." (PMID 35056105, 2021). "Taken together, our results unravel a detrimental role of TYK2 in cutaneous candidiasis and provide insights into the immune response to local fungal infections." (PMID 39622833, 2024). "Inhibiting Tyk2 activation might be associated with an ideal balance between efficacy and safety because individuals with deactivating genetic variants of Tyk2 are highly protected from some IMIDs but do not exhibit an increased risk of hospitalization for mycobacterial, viral, or fungal infections." (PMID 36834806, 2023). "Moreover, there are still gaps in our understanding of how TYK2 balances host-protective and disease-promoting immunity in vivo, in particular in response to fungal infections and at tissue barriers." (PMID 39622833, 2024). "Tyk2 null mice have poor IFN and IL-12 responses, leading to exacerbated bacterial, viral, and fungal infections." (PMID 35056105, 2021).
gastric cancer (4 papers, 2021 to 2024). A primary or metastatic malignant neoplasm involving the stomach. "Including JAK1, JAK2, JAK3, and Tyk2, various JAKs are always activated by cytokines to mediate the gastric cancer cells progression, such as JAK1 kinase by IL-10 family cytokines, JAK2 kinase by G-CSF factor, Tyk2 kinase by cytokine IL-23, respectively." (PMID 35734442, 2022). "Therefore, TYK2 and JAK3 may function as biomarkers in stomach cancer, as they are associated with tumor aggressiveness and metastasis." (PMID 34439323, 2021). "Our data show a decrease in the phosphorylation of TYK2 at Y292 and STAT3 at Y705 and Y737 on inhibition of CAMKK2 in gastric cancer." (PMID 35646067, 2022). "We have reported decreased phosphorylation of TYK2 at Y292, PTK2 at Y662, and STAT3 at Y705, Y737 upon inhibition of CAMKK2 in gastric cancer cells." (PMID 35646067, 2022). "The IMAGiC model predicts response to ICI in patients with advanced gastric cancer based on the expression signature of four genes (ubiquitin C-terminal hydrolase L1 [UCHL1], tyrosine kinase 2 [TYK2], protein kinase D1 [PRKD1], and armadillo repeat-containing X-Linked 1 [ARMCX1])." (PMID 37877810, 2024).
glioblastoma (4 papers, 2023 to 2026). The most malignant astrocytic tumor (WHO grade IV). "It is similar to the findings of PUS7 in other malignancies, which have been reported to affect glioblastoma growth and tumorigenesis by regulating TYK2 translation through tRNA-dependent pseudouridylation." (PMID 37420297, 2023). "For instance, PUS7 facilitates pseudouridylation at Ψ50 in several tRNA isoforms, involving tRNA‐Arg‐CCG, tRNA‐Gln‐CTG, tRNA‐Asp‐GTC, tRNA‐Glu‐CTC, and tRNA‐Tyr‐GTA, enhancing the translation of tyrosine kinase 2 (TYK2) by mediating the transport of specific amino acids in glioblastoma." (PMID 39834094, 2025). "Recently, it has been reported that PUS7 can serve as an underlying biomarker for glioma in a neurological tumor, glioblastoma, and up-regulated PUS7 increased Ψ modification in tRNA and decreased TYK2 translation can promote tumor progression through the interferon-STAT1 pathway." (PMID 37420297, 2023). "In glioblastoma, PUS7 targets the tRNA for pseudouridylation, affecting the interferon-STAT1 pathway and cell growth by reducing Tyk2 translation." (PMID 41554761, 2026).
hypothyroidism (4 papers, 2023 to 2025). Abnormally low levels of thyroid hormone. "We observed converging evidence linking both common and rare PAVs in TYK2 and ZAP70 with reduced risk of hypothyroidism." (PMID 41238958, 2025). "A comprehensive approach integrating PLACO, Bayesian colocalization analysis, MTAG, and TWAS, we successfully identified TYK2, IL2RA, and IRF5 as shared risk genes for both hypothyroidism and RA." (PMID 38332917, 2023). "Among these, 12 genes, including TYK2 and IRF5, were implicated in RA (discovery), RA (replication), and hypothyroidism, according to TWAS." (PMID 38332917, 2023). "TYK2 was consistently identified by all four methods used, while IL2RA and IRF5 were identified in the hypothyroidism and RA (replication) studies using two or three of these methods." (PMID 38332917, 2023). "This comprehensive approach identified TYK2, IL2RA, and IRF5 in hypothyroidism and RA (discovery) utilizing four or three methods." (PMID 38332917, 2023).
multiple myeloma (4 papers, 2010 to 2025). "We further examined whether tubulosine could affect IFN‐α‐induced JAK1‐ and/or TYK‐2 signalling in multiple myeloma U266 cells." (PMID 32558259, 2020). "As described in this review, inhibitors of half of these (PLK1, TYK2 and AURKB) have been studied to one degree or another as potential targets in MM while the other three represent fertile ground for new anti-myeloma development." (PMID 27655636, 2016). "Immunoprecipitates of TYK2 were derived from multiple myeloma U266 cells following treatment with IFN-α, a known activator of TYK2." (PMID 20149240, 2010).
primary immunodeficiency (4 papers, 2015 to 2025). "In conclusion, we identified novel compound heterozygous mutations in TYK2 associated with primary immunodeficiency characterized by a rare type of EBV-associated B-cell lymphoma and T-cell lymphopenia." (PMID 29725107, 2018). "Complete LOF of TYK2 leads to human primary immunodeficiency, which is caused by rare autosomal recessive null mutations in TYK2 and results in increased risk of severe infections (bacterial, viral and fungal)." (PMID 25849893, 2015). "The results demonstrated that TYK2 might be involved in T cell activation and keratinization, and was associated with the risk factors for HNSCC, including primary immunodeficiency." (PMID 36531252, 2022).
acute myeloid leukaemia (3 papers, 2020 to 2025). "A TYK2 single-nucleotide polymorphism (SNP) in the kinase domain (P1104A) has been associated with different types of tumours and has been found in about 7% of acute myeloid leukaemia (AML) patients." (PMID 33260630, 2020). "Furthermore, high-throughput sequencing of the kinase domains of tyrosine kinase genes identified a SNP, rs2304255 (TYK2-G363S), in the TYK2 kinase domain that was associated with acute myeloid leukemia (AML), although it is unclear as to the impact of this mutation on TYK2 function." (PMID 34439323, 2021).